RRBP1 (ribosome binding protein 1)
Description:
Acts as a ribosome receptor and mediates interaction between the ribosome and the endoplasmic reticulum membrane.
Synonyms: RRp; ES/130; hES; p180; ES130
Tractability: Antibody: UniProt predicts a signal peptide or a membrane-spanning region. PROTAC: UniProt records ubiquitination sites on it; ubiquitination databases record sites on it; its protein half-life has been measured.
Gene: Protein-coding gene on chromosome 20 (17,613,678 to 17,682,295, reverse strand). Ensembl gene ENSG00000125844.
Subcellular location: Endoplasmic reticulum membrane
Subcellular location (Human Protein Atlas): Endoplasmic reticulum
Pathways (Reactome):
Disease: Dengue Virus Genome Translation and Replication; Signaling by ALK fusions and activated point mutants
Gene Ontology:
Molecular function: protein binding; RNA binding; signaling receptor activity
Biological process: osteoblast differentiation; translation; protein transport
Cellular component: endoplasmic reticulum; membrane; endoplasmic reticulum membrane; ribosome
Genetic constraint (gnomAD): Loss-of-function variants: 92 observed, 155.31 expected, observed/expected ratio (o/e) 0.59, 90% interval 0.5 to 0.7. The upper end of that interval is the gene's LOEUF score, 0.7, which puts it in group 2 of 6, group 1 being the genes least tolerant of losing a copy. Missense variants: 1,663 observed, 1,738.2 expected, observed/expected ratio (o/e) 0.96, 90% interval 0.92 to 1. Synonymous variants: 672 observed, 692.58 expected, observed/expected ratio (o/e) 0.97, 90% interval 0.91 to 1.03.
Homologues: Orthologues: chimpanzee RRBP1 (93% identical), macaque RRBP1 (90% identical), dog RRBP1 (86% identical), pig RRBP1 (84% identical), mouse Rrbp1 (82% identical), rat Rrbp1 (82% identical), rabbit RRBP1 (78% identical), guinea pig RRBP1 (52% identical), tropical clawed frog rrbp1 (40% identical), zebrafish rrbp1a (35% identical), zebrafish rrbp1b (29% identical), Drosophila melanogaster alt (16% identical).
Diseases named in the same sentence as RRBP1 in open-access papers:
RRBP1 is named in the same sentence as 46 diseases in open-access papers, as found by Europe PMC text mining. Sharing a sentence is not in itself a finding about the gene and the disease. The quoted sentences say what the papers report.
lung carcinoma (11 papers, 2015 to 2026). "In addition, RRBP1 is markedly upregulated in lung cancer tissues and its upregulation is associated with early tumor stages." (PMID 41200062, 2026). "In lung cancer, breast cancer and CRCs, RRBP1 stabilizes GRP78 mRNA, thereby enhancing UPR-mediated survival under ERS." (PMID 41200062, 2026). "RRBP1 reportedly alleviates ER stress-induced apoptosis in lung cancer cells by enhancing GRP78 expression." (PMID 38360615, 2024). "We performed IHC using specific antibodies against USP35 and RRBP1 on 45 lung cancer tissue samples." (PMID 34618999, 2022). "The upregulated expression of RRBP1 in lung cancer, colorectal cancer, endometrial endometrioid adenocarcinoma, ovarian, breast, and bladder cancer leads to poor prognosis." (PMID 34445467, 2021). "RRBP1 enhances the expression GRP78 to make lung cancer cells resistant to chlamycin, 2-deoxyglucose, and doxorubicin." (PMID 33743739, 2021). "Earlier research reports on RRBP1 in tumors, including breast cancer, [lung cancer, and colorectal cancer, have found that RRBP1 plays an important role in the prognosis of tumors." (PMID 31285390, 2019). "Currently, ribosome-binding protein 1 (RRBP1) is considered to be a novel oncogene that is overexpressed in colorectal cancer, lung cancer, mammary cancer, esophageal cancer and other carcinomas." (PMID 30684972, 2019). "Recently, RRBP1 has been confirmed to be overexpressed in lung cancer, breast cancer, colorectal cancer, and esophageal cancer." (PMID 30684972, 2019). "Our findings are in agreement with the previous studies on the roles of RRBP1 in tumor progression in various cancers, such as lung cancer, breast cancer, colorectal cancer and esophageal cancer." (PMID 30684972, 2019). "Also, RRBP1 is reported to be overexpressed in lung cancer and its overexpression alleviates ER stress via enhancing GRP78 expression in lung cancer cells." (PMID 34618999, 2022). "RRBP1 is overexpressed in lung cancer and promotes tumor cell survival." (PMID 27689402, 2016). "In lung cancer, the USP35 deubiquitination modification inhibits the proteasome-mediated degradation pathway, whereas in prostate cancer, METTL3 stabilizes RRBP1 through m6A modification." (PMID 41200062, 2026). "RRBP1 enhances GRP78 protein expression and regulates UPR, which allows it to adapt to ER stress to maintain the tumorigenicity of lung cancer." (PMID 33743739, 2021). "Research results have shown that RRBP1 knockdown can affect the stability of ATF6 and GRP78 mRNA, thereby reducing the in vivo tumorigenicity of lung cancer cells." (PMID 31285390, 2019). "Therefore, RRBP1 regulates the UPR by maintaining the mRNA stability of GRP78, which in turn helps lung cancer cells adapt to ERS and chemotherapeutic stress and maintains tumor survival and progression." (PMID 41200062, 2026). "Ribosome‐binding protein 1 (RRBP1) was found to positively correlate with ubiquitin‐specific protease 35 (USP35) levels by proteomic analysis, which was validated in genetically modified cells and human non‐small cell lung cancer (NSCLC) tissues." (PMID 34618999, 2022). "These genes have diverse cellular roles, among which RRBP1 functions in endoplasmic reticulum stress response and has been found upregulated in lung cancer, and overexpression of the ID3 transcriptional repressor has been reported to reduce lung cancer growth in vivo." (PMID 26556242, 2015).
breast carcinoma (7 papers, 2012 to 2026). "The mRNA and protein expression levels of RRBP1 in breast cancer tissues are markedly higher compared with those in normal tissues." (PMID 41200062, 2026). "The RRBP1 is highly expressed in a variety of cancers, including lung, ovarian, prostatic, esophageal, rectal, and breast cancer." (PMID 34445467, 2021). "Overexpression of Rrbp1 was found in patients with lung, colorectal, and breast cancers, of which predict an undesirable outcome." (PMID 27699085, 2016). "The results we obtained from our experiment show that RRBP1 was significantly upregulated in breast cancers." (PMID 22709790, 2012). "Our findings suggest that RRBP1 is an interesting molecule that can be further studied for its potential to serve as a breast cancer biomarker." (PMID 22709790, 2012). "Immunohistochemical labeling of breast cancer tissue microarrays was carried out to determine the expression of RRBP1 in a large panel of breast cancers." (PMID 22709790, 2012). "We selected RRBP1 as one such candidate to further validate its protein expression across a panel of breast carcinomas using immunohistochemistry." (PMID 22709790, 2012). "Notably, RRBP1 is upregulated in various cancer types, such as breast cancer, colorectal cancer and bladder cancer, and its expression levels are positively associated with advanced clinical stages and poor prognosis." (PMID 41200062, 2026). "RRBP1 upregulation markedly influences survival in patients with early-stage breast cancer, but this association has not been observed in patients with advanced-stage types of cancer." (PMID 41200062, 2026). "RRBP1 is also a biomarker for poor prognosis in colorectal, prostate, and breast cancers." (PMID 34445467, 2021). "Additionally, RRBP1 has become a potential marker of poor prognosis in colorectal cancer and breast cancer." (PMID 31285390, 2019). "We found that RRBP1 was overexpressed in 84% (177/219) of breast carcinoma cases tested." (PMID 22709790, 2012). "RRBP1, as a consequence of its overexpression, could possibly leak into blood plasma and show up at detectable levels in breast carcinomas." (PMID 22709790, 2012). "RRBP1 promotes breast cancer cell survival by participating in the UPR and this mechanism might underlie its association with poor prognoses in patients with HER-2+ breast cancer." (PMID 41200062, 2026). "RRBP1 expression and lymph node metastasis (LNM) are independent prognostic factors for OS in patients with HER-2+ breast cancer, according to a multivariate analysis." (PMID 41200062, 2026). "RRBP1 expression is higher in malignant breast cancer types compared with that in benign or proliferative lesions; however, no gradient in RRBP1 expression has been observed in benign or proliferative conditions." (PMID 41200062, 2026).
colorectal cancer (6 papers, 2019 to 2026). A primary or metastatic malignant neoplasm that affects the colon or rectum. "RRBP1 mRNA is higher in colorectal cancer (CRC) tissues compared with normal tissues and RRBP1 protein is less variable in normal tissues but more heterogeneous in cancerous tissues." (PMID 41200062, 2026). "Colorectal cancer patients with high RRBP1 expression had shorter disease specific survival compared to those with low RRBP1 expression." (PMID 33035235, 2020). "RRBP1 overexpression promotes the progression of esophageal cancer and colorectal cancer, and is helpful for predicting patient outcomes." (PMID 30684972, 2019). "Additionally, RRBP1 has been identified as a potential protein marker for colorectal cancer." (PMID 40663520, 2025).
bladder cancer (4 papers, 2021 to 2026). "We analyzed the relationship between RRBP1 and genes involved in bladder-cancer-associated or YAP1-mediated chemoresistance and genes." (PMID 34445467, 2021). "These analyses of TCGA bladder cancer data demonstrated that RRBP1 was an oncogene that was associated with poor prognosis." (PMID 34445467, 2021). "Experimental overexpression of RRBP1 has been found to promote the proliferation of bladder cancer cells, whereas downregulation of RRBP1 inhibits cell proliferation." (PMID 41200062, 2026). "The mRNA and protein expression levels of RRBP1 in bladder cancer tissues are markedly higher compared with that in normal bladder tissues." (PMID 41200062, 2026). "RRBP1 is highly expressed in advanced-stage, LNM and basal squamous subtype bladder cancer and is closely associated with poor prognosis in patients." (PMID 41200062, 2026). "High expression of RRBP1 reduced the overall survival of patients with bladder cancer, which might, at least in part, be due to its effects on CCR7." (PMID 35203305, 2022). "Meanwhile, RRBP1 overexpression promotes migration and invasion of bladder cancer cells." (PMID 34618999, 2022). "Bladder cancer patients with high RRBP1 expression display shorter overall survival." (PMID 34618999, 2022). "We further explored whether RRBP1 expression was correlated with cancer stage, nodal metastasis status, and molecular subtypes in bladder cancer." (PMID 34445467, 2021). "As the expression of RRBP1 is related to migration and invasion in bladder cancer, we next determined whether the elimination of RRBP1 in the cell line inhibited cell mobility." (PMID 34445467, 2021). "Unfortunately, an experiment to add back RRBP1 was not conducted to validate the role of CCR7 in bladder cancer migration/invasion." (PMID 35203305, 2022). "While not well defined, RRBP1 knockdown led to an elevation in CCR7 mRNA as well; however, the levels of CCR7 protein decreased presumably due to reduced CCR7 mRNA translation in the low RRBP1 environment with the consequence of attenuated bladder cancer cell migration and invasion." (PMID 35203305, 2022). "Ribosome-binding protein 1 (RRBP1), an endoplasmic reticulum membrane protein required for ribosome binding and protein transportation is a marker of some solid cancers and is highly expressed in bladder cancer cell lines compared to transformed non-cancerous urethral cells." (PMID 35203305, 2022).
hepatocellular carcinoma (4 papers, 2016 to 2026). A malignant tumor that arises from hepatocytes. "It has been reported that the IRES activity of 51 UTR of RRBP1 mRNA enhances the expression of RRBP1 protein, which makes hepatoma cell BEL7402 cells play a role in cellular immunity and promote the occurrence of liver cancer." (PMID 30684972, 2019). "In hepatocellular carcinoma (HCC) studies, RRBP1 has been shown to serve a key role in high glucose-mediated tumor malignant progression through the E2F transcription factor 1 (E2F1)/RRBP1 signaling pathway." (PMID 41200062, 2026). "To investigate whether the expression of RRBP1 was affected during cellular stress, we measured the endogenous protein and mRNA levels of RRBP1 in human hepatocellular carcinoma cells (Bel7402) treated with paclitaxel (PTX) and adriamycin (ADM), which are applied as chemotherapy drugs in cancer." (PMID 27447629, 2016). "Moreover, the RRBP1 expression is induced by chemotherapeutic drug paclitaxel or adriamycin in human hepatocellular carcinoma cells and accompanied with the increased expression of La autoantigen (La), which binds to RRBP1 IRES element and facilitates translation initiation." (PMID 27447629, 2016). "In addition, RRBP1 protein expression was tested in human hepatocellular carcinoma cells following treatment with inducers of cell stress and La may contribute to regulate RRBP1 IRES-mediated translation initiation during cellular stress conditions." (PMID 27447629, 2016). "La stimulated the IRES activity of RRBP1 under stress conditions and the enhanced IRES activity, resulting in the increase of RRBP1 protein expression in Bel7402 cells, indicating the significant role of RRBP1 IRES response to cellular stress in hepatocellular carcinoma cells." (PMID 27447629, 2016).
lymph node metastasis (3 papers, 2019 to 2021). "RRBP1 expression was also significantly increased in EC patients with lymph node metastasis (P = 0.021)." (PMID 30684972, 2019). "Increased expression of RRBP1 was also observed in tumor tissues with regional lymph node metastasis (N1 and N2) compared to those with no regional lymph node metastasis (N0)." (PMID 34445467, 2021). "High levels of expression of RRBP1 were strongly correlated with pathological features, such as the Federation of Gynecology and Obstetrics (FIGO) stage, histological grade, depth of myometrial invasion and lymph node metastasis (P < 0.05)." (PMID 30684972, 2019). "Moreover, the high RRBP1 expression in epithelial ovarian cancer was closely related to Federation International of Gynecologie and Obstetrigue (FIGO) stage (P<0.001), histological grade (P=0.021), histological type (P=0.004), and lymph node metastasis (P=0.012)." (PMID 31285390, 2019).
acute myeloid leukemia (2 papers, 2019 to 2026). Acute myeloid leukemia (AML) is a group of neoplasms arising from precursor cells committed to the myeloid cell-line differentiation. "In acute myeloid leukemia (AML), RRBP1 has been reported as a potential leukemogenesis-associated molecule regulated by exosomes derived from bone marrow microenvironmental mesenchymal stromal cells." (PMID 41200062, 2026). "It has also been reported that RRBP1 may be involved in the development of acute myeloid leukemia." (PMID 30684972, 2019).
Obesity (2 papers, 2022 to 2024). Accumulation of substantial excess body fat. "In the last part of our work, we tested whether decreased rough ER-mitochondria interactions in obesity could be related to alterations in RRBP1 abundance." (PMID 38729945, 2024). "The decrease in rough ER-mitochondria interactions in obesity could result from an overall decrease in the abundance of rough ER sheets, as we’ve previously shown, combined with the marked downregulation of RRBP1." (PMID 38729945, 2024). "Therefore, the results of proteomic analyses indicate that the ER proteins such as RRBP1, CRELD2 and PDIA3 in the exosomes were differentially regulated by the obesity-associated OS condition in the caput epididymis and may indeed affect sperm maturation." (PMID 36411474, 2022). "Thus, in the current study, the differential expression of RRBP1, CRELD2 and PDIA3 in exosomes may indeed attribute to obesity-induced ER stress." (PMID 36411474, 2022). "However, whether RRBP1 expression and localization is modulated by fasting and obesity and is required for ER remodeling in fasting has never been tested." (PMID 38729945, 2024).
pituitary adenoma (2 papers, 2023 to 2025). "Moreover, circVPS13C interacts with RRBP1 to increase pituitary adenoma growth by reducing the stability of IFITM1 mRNA." (PMID 40612865, 2025).
prostate carcinoma (2 papers, 2022 to 2026). A carcinoma that arises from epithelial cells of the prostate gland. "As a potential oncogene, increased RRBP1 expression has been linked to certain bone metastatic cancer cells, including lung, breast, and prostate cancers." (PMID 36568157, 2022). "Furthermore, RRBP1 expression is associated with the T stage of prostate cancer, LNM and prostate-specific antigen level." (PMID 41200062, 2026). "Therefore, RRBP1 is closely associated with tumor malignancy and progression and high RRBP1 expression can serve as a diagnostic marker and a predictor of poor prognosis in prostate cancer." (PMID 41200062, 2026). "In summary, RRBP1 is a core effector molecule of the METTL3/m6A signaling axis in prostate cancer and its m6A-dependent stabilization promotes tumor aggressiveness and is closely associated with poor patient prognosis." (PMID 41200062, 2026). "The median survival time is shorter in patients with prostate cancer with higher compared with lower RRBP1 expression." (PMID 41200062, 2026). "The mRNA and protein expression levels of RRBP1 are higher in prostate cancer tissues compared with those in normal cancer-adjacent tissues." (PMID 41200062, 2026). "Breast and prostate cancer cells, MDA-MB-231 and PC3, were cultured, respectively, followed by collecting conditioned mediums (CMs) and identifying the abundance of RRBP1 in CMs using LC-MS/MS." (PMID 36568157, 2022). "In this study, we identified the abundance of RRBP1 protein in the conditioned mediums (CMs) from human breast cancer cell line MDA-MB-231 and prostate cancer cell line PC3, respectively." (PMID 36568157, 2022).
Arrhythmia (1 paper, 2023). Any cardiac rhythm other than the normal sinus rhythm. "Consistently, we found that Rrbp1- knockout (KO) mice had lower blood pressure and hyporeninemic hypoaldosteronism, which cause severe hyperkalemic cardiac arrhythmia-induced sudden death." (PMID 36803854, 2023). "The survival of Rrbp1-KO mice significantly decreased under high potassium intake due to lethal hyperkalemia-induced arrhythmia and persistent hypoaldosteronism, which could be rescued by fludrocortisone." (PMID 36803854, 2023). "The terminal rhythms were compatible with arrhythmia caused by hidden hyperkalemia, without detailed pathological and structural abnormalities in the hearts, coronary arteries, aortas or whole brains of Rrbp1-KO mice." (PMID 36803854, 2023). "The cardiac rhythms of 12–16-week-old mice were monitored by telemetry ECG with and without high K+ intake to determine if the death of Rrbp1-KO mice under high K+ intake was related to life-threatening arrhythmia." (PMID 36803854, 2023).
cholangiocarcinoma (1 paper, 2026). A carcinoma that arises from the intrahepatic biliary tree (intrahepatic cholangiocarcinoma) or from the junction, or adjacent to the junction, of the right and left hepatic ducts (hilar cholangiocarcinoma). "By contrast, because the RRBP1 gene in cholangiocarcinoma, uterine carcinosarcoma, thyroid carcinoma, mesothelioma and kidney chromophobe demonstrated no changes, the oncogenic role of RRBP1 in these cancer types may be limited." (PMID 41200062, 2026).
colon carcinoma (1 paper, 2024). "Analysis of data from TCGA and GTEX revealed increased levels of RRBP1 in multiple tumors, including colon cancer." (PMID 38360615, 2024).